CD36 (CD36 molecule (CD36 blood group))
Diseases named in the same sentence as CD36 in open-access papers (continued):
Sharing a sentence is not in itself a finding about the gene and the disease.
malaria (continued). "However, we did see a possible reduction in CD36 binders in adults with multiple severe malaria complications." (PMID 31040236, 2019). "In malaria, CD36 plays several roles, including (i) mediating the sequestration of P. falciparum in vascular capillaries through the binding of adhesive PfEMP1 expressed on the surface of IRBCs, (ii) phagocytic uptake of parasites, and (iii) enhancing innate immune responses." (PMID 30619355, 2018). "Hemoglobin AC, which reduces severe malaria risk, reduced IE binding to the receptors CD36 and integrin α5β1, while hemoglobin AS did not modify IE adhesion to any receptors." (PMID 29066816, 2017). "First, they provide evidence that CD36 and EPCR binding have early origins and have been maintained in the populations of both P. reichenowi and P. falciparum parasites, despite the association of EPCR binding with severe malaria in human infections." (PMID 28101534, 2017). "Severe malaria risk varies with age, but age significantly impacted the level of IE binding to only a few receptors: IE binding to JAM-B decreased with age, while binding to CD36 and integrin α5β1 significantly increased with age." (PMID 29066816, 2017). "CD36 is a ubiquitously expressed scavenger receptor and a major receptor for the Plasmodium falciparum erythrocyte membrane protein 1 family of erythrocyte surface proteins, responsible for sequestration and rosetting of malaria-infected red blood cells." (PMID 28541483, 2017). "Although this seems contradictory to the known protective effect of SAO during severe malaria, it is worth noting that CD36 is an important immune cell receptor, and has been implicated in the binding and removal of parasitized erythrocytes by both platelets and phagocytic cells." (PMID 26215182, 2015). "In addition, a previous report showed that circulating monocytes from malaria-infected patients presented decreased CD36 protein expression." (PMID 26385579, 2015). "Testing the binding of parasites from HbAS, HbAC, and HbAA children with malaria to individual receptors (e.g., CD36, ICAM-1, gC1qR, EPCR) as well as to MVECs derived from brain or lung may help to further clarify the binding phenotypes of these parasites." (PMID 24647281, 2014). "Since parasites from these children show increased binding to CD36 and ICAM-1, the PfEMP1 variants causing uncomplicated malaria in HbAS children might share features with those causing severe malaria in other children." (PMID 24647281, 2014). "Differential affinity of individual DBLs and CIDRs for specific host endothelial receptors (e.g., EPCR in the brain and CD36 in other organs) enables the organ-specific sequestration of parasitized RBCs and influences the clinical presentation and severity of malaria." (PMID 24647281, 2014). "Furthermore, since the contribution of CD36 is particularly evident at low doses of infected erythrocytes, the results imply that the effect of CD36 on malaria immunity is imprinted early during infection when parasite load is low." (PMID 24204889, 2013). "The IRBC-dose dependent pro-inflammatory cytokine responses suggests that CD36 regulate malaria immunity at the early stages of infection when IRBC load is low, and that the early immune responses appear to substantially influence the subsequent development of malaria immunity." (PMID 24204889, 2013). "Thus, it is tempting to predict that the effect induced by CD36 early on during infection leads to programming of DCs to modulate immunity to malaria." (PMID 24204889, 2013). "In addition, the data point to the possibility that parasite- or host-derived ROS serve to enhance the CD36-mediated increases in paracellular fluid conductance during malaria." (PMID 23967147, 2013).
malaria (continued). "Given that DCs respond to malaria parasites very early during infection and influence development of immunity, and that CD36 contributes substantially to the cytokine production by DCs, NK and T cells, our results suggest that CD36 plays an important role in immunity to malaria." (PMID 24204889, 2013). "CD36 is an integral membrane protein found on the surface of many cell types and binds many ligands including oxidized lipid proteins, long-chain fatty acids and erythrocytes that are parasitized with the malaria parasite Plasmodium falciparum." (PMID 23236364, 2012). "In addition, recent advances in our current understanding of the biological actions of PPARγ on CD36 and malaria clearance from the hosts are highlighted." (PMID 22287954, 2012). "The effects of CD36 in malaria have likewise been particularly controversial." (PMID 22909232, 2012). "However, in inflammatory conditions, we demonstrated that Nrf2 pathway controls CD36 expression and improves the outcome of severe malaria independently of PPARγ." (PMID 21949655, 2011). "Moreover, rosiglitazone and IL13 have been shown to promote in vitro an increase in CD36-mediated phagocytosis and a decrease in malaria parasite-induced TNF-α release both on murine macrophage and human monocytes." (PMID 21949655, 2011). "In conclusion, the present results provide direct evidence that inflammatory processes and particularly malaria parasite-induced inflammatory processes impair CD36 expression on Swiss murine as on human MDMs and CD36-mediated phagocytosis, favoring the worsening of malaria infection." (PMID 21949655, 2011). "BPI was used to identify the main host receptor involved in sequestration of the murine malaria parasite P. berghei, the highly conserved class II scavenger receptor CD36, which is also the main receptor for erythrocytes infected with the human malaria parasite Plasmodium falciparum." (PMID 20955395, 2011). "Here we have examined the relationship between specific adhesion phenotypes of P. falciparum isolates, namely, adhesion to ICAM1, CD36 and gC1qR, rosetting and platelet-mediated clumping, and disease severity in children less than 5 years of age residing in a malaria-endemic area of Mozambique." (PMID 21559373, 2011). "In fact, the role of the CD36 gene in malaria is still debated and raises the question of whether different studies may capture different effects of the CD36 gene variants in severe and in cerebral malaria." (PMID 20585394, 2010). "In summary, ALI induced by experimental murine malaria was CD36-dependent." (PMID 18483551, 2008). "Studies with different human populations with CD36 polymorphisms failed to attribute a clear role to CD36 expression in human malaria." (PMID 17367535, 2007). "Thus, the role of CD36 in the pathology of human malaria remains elusive and CD36-mediated adhesion cannot be considered as a validated target for anti-malarial intervention." (PMID 17367535, 2007). "Studies on human populations polymorphisms for CD36 failed to define a clear role for CD36 in severe malaria syndromes." (PMID 17367535, 2007). "In addition, reticulocytes might be preferred, as CD36 was investigated concordantly with ligands from the malaria parasite, and the result can be interpreted directly with regard to malaria pathophysiology." (PMID 37981686, 2023). "It is possible that in this study population of patients with severe malaria, endothelial receptors other than CD36 play a larger role mediating sequestration in the systemic circulation, thus reducing the potential effect of levamisole, which specifically inhibits cytoadherence to CD36." (PMID 23943850, 2014). "In contrast to the conclusion that CD36 is a major determinant in severity of malaria, such as CM, some recent results indicated that increased binding to CD36 by parasites is associated with uncomplicated malaria but not CM because little CD36 is expressed on brain microvasculature." (PMID 23967200, 2013).
malaria (continued). "Importantly, our observations that NK and T cells stimulated by CD36-adherent IRBC-activated WT DCs produce substantially higher levels of IFN-γ than those stimulated with similarly activated Cd36−/− DCs support the notion that CD36 plays an important role in malaria immunity." (PMID 24204889, 2013). "However, the role of CD36 in the development of immunity to malaria remains poorly understood." (PMID 24204889, 2013). "CD36 (Platelet glycoprotein IV) has been consistently found to be a major ligand for adhesion of iRBC expressing PfEMP-1, and it enhances phagocytosis and host clearance of the parasite in the spleen, but its exact role in the pathogenesis of malaria remains unresolved." (PMID 24098393, 2013). "In addition, Fyn, a CD36-associated tyrosine kinase, was shown to exhibit an altered intracellular distribution and activation status in CD36−/− LMVECs and to be critical for CD36-mediated increases in pulmonary endothelial cell fluid conductance during malaria." (PMID 23967147, 2013). "Interestingly, CD36 deficiency did not attenuate the malaria-induced decrease in the reflection coefficient (σalb)." (PMID 23967147, 2013). "The nearly identical phenotype in the CD36−/− and Fyn−/− mice supports the hypothesis that CD36 and Fyn are functionally linked in the mechanism that regulates pulmonary endothelial barrier integrity in malaria." (PMID 23967147, 2013). "In any event, although the CD36 functional deficiency in different populations may cause different effects in response to malaria infection, the results of all these studies are consistent with our conclusion here that CD36 significantly modulates immune responses to malaria." (PMID 24204889, 2013). "Additionally, rs3211938-G has been shown in previous studies to be associated with CD36 deficiency and with susceptibility to malaria, although this has not been confirmed in other studies." (PMID 23236364, 2012). "In a murine model of malaria, administration of the PPARγ agonist rosiglitazone, to Plasmodium chabaudi-infected mice, significantly decreased parasitaemia levels in wild type compared to CD36 knock-out mice and improved survival in Plasmodium berghei-ANKA infected groups." (PMID 21411011, 2011). "However, when the binding levels to ICAM-1Ref and CD36 were correlated, no significance was observed either among isolates causing severe (r = 0.197, p = 0.153) or among isolates causing uncomplicated malaria (r = 0.309, p = 0.076)." (PMID 19650937, 2009). "Similarly among children with severe malaria in Africa, parasite binding to CD36 was inversely related to disease severity, but another study found that CD36 binding was equivalent between parasitized erythrocytes derived from CM patients or community controls." (PMID 18483551, 2008). "Cellular adhesion of P. falciparum-iRBCs consists of a rolling interaction with ICAM1 and a stationary interaction with CD36 and EPCR on vascular endothelial cells which leads to severe malaria." (PMID 40294074, 2025). "CD44, CD36 and ICAM1 have been previously reported to play an important role in malaria pathophysiology." (PMID 38828264, 2024). "To analyze the specific molecular interaction of PvMTRAP and CD36, we next included MTRAP proteins from different human-infecting malaria in the same ELISA methodology." (PMID 37981686, 2023). "Among them, malaria, PPAR signaling, and the adipocytokine signaling pathway reached statistical significance (FDR value of <1 and p < 0.05) and included TGFB1, CD36, THBS1, FABP1, PCK1, and IRS1." (PMID 36193307, 2022). "Six genes (TGFB1, CD36, THBS1, FABP1, PCK1, and IRS1) were involved with malaria, PPAR signaling, and the adipocytokine signaling pathway." (PMID 36193307, 2022). "It is possible that, similar to CD36, other scavenger receptors, such as MARCO modulate innate immunity to malaria to a certain extent." (PMID 30619355, 2018).
malaria (continued). "E8B is a malaria strain that expresses a mixture of var genes that, in contrast to CS2, promote binding to CD36 and ICAM-1." (PMID 26149666, 2015). "CD36 and TLR2 collaboration leads to a pro-inflammatory response via ERK, p38, MAPK, JNK and NF-kB signaling following interaction with malaria-GPI anchors." (PMID 26385579, 2015). "CM isolates bind significantly more to CD36 than to ICAM-1, which was correlated with high transcription level of group B var genes, supporting their implication in malaria pathogenesis." (PMID 25156105, 2014). "Our results also points to an interesting notion that the expression of high levels of CD36 and selective expression of TLR9 by human pDCs is an evolutionary adaptation for the effective immune responses to malaria during the long course of their co-existence." (PMID 24204889, 2013). "The aim of the study was to find possible associations between the membrane expression of ICAM-1 and the plasma levels of antibodies to CD36- and ICAM-1-binding VSAs on one hand, and the development of cerebral complications in malaria patients." (PMID 24386348, 2013). "The importance of Fyn in CD36-dependent endothelial signaling was confirmed using in vitro Fyn knockdown as well as Fyn−/− mice, which were also protected from H2O2- and malaria-induced lung endothelial leak, respectively." (PMID 23967147, 2013). "The ICAM 1 and CD36 genes have also been related to ECM in the mouse models but investigations on the role of these genes in human CM and severe malaria led to inconclusive and often contradictory results." (PMID 20585394, 2010). "In inflammatory conditions such as malaria, cytokines like TNF-α and IFNγ decrease the expression of peroxisome proliferator–activated receptor γ (PPARγ), a nuclear receptor acting as a transcription factor and promoting CD36 in macrophages." (PMID 38988513, 2024). "Another important scavenger receptor for PS, CD36, was implicated mainly in the RBC removal in malaria, which affects both infected and non-parasitized RBCs." (PMID 34573346, 2021). "PfEMP1 has been found to bind to CD36 on platelets via CIDRα2-6 domains in uncomplicated/mild malaria (UM/MM), and to ICAM-1 on endothelial cells in severe malaria (SM) via DBLβ5 domains." (PMID 32153634, 2020). "Among the PfEMP1 receptors in human endothelium, the most common is the broadly expressed in human cell CD36, but PfEMP1 binding to CD36 is not related to any specific form of malaria." (PMID 31251748, 2019). "As P. chabaudi AS iRBCs still sequester in the absence of CD36 it is clear that CD36 is not a major receptor for tissue cytoadherence in this experimental model of malaria." (PMID 28468674, 2017). "Furthermore, one has to bear in mind that receptors such as CD36 are ubiquitously expressed and relevant to many disease processes—e.g., CD36 not only is a major receptor for oxidized LDL, but also plays an important role in malaria pathogenesis." (PMID 25484870, 2014). "The heterogeneity of the vascular endothelium in various locations in the body, characterized by the difference in expression levels of CD36 or ICAM-1 may play an important role in determining the type and severity of malaria." (PMID 23967200, 2013). "Further evidence of Fyn dysregulation in the absence of CD36 was obtained from malaria-infected CD36−/− lungs where it was demonstrated that the levels and activation status of Fyn were altered." (PMID 23967147, 2013). "In the case of mouse malaria, although the parasite ligand involved has not been identified, studies have shown that CD36 mediates the sequestration of rodent malaria parasite in lungs and adipose tissues." (PMID 24204889, 2013). "Genetic alterations in the CD36 gene influence the malaria outcome, regardless of different conclusions concerning the polymorphisms identified in this molecule, perhaps reflecting differences among the populations and clinical spectrums of the disease." (PMID 23316245, 2012).
malaria (continued). "The effects of polymorphisms in a number of genes, including β-globin, G6PD, TNF-α, IFN-γ, CD36, ICAM-1, IL10, IL4R, and LTA, upon the clearance of malaria parasites in African individuals was investigated across five large association studies from Burkina Faso, Cameroon, Kenya, Mali, and Sudan." (PMID 21867552, 2011). "SNP genotypes in some known malaria candidate genes were not differentially distributed between malaria cases and controls, including SNPs in CD36, which were monomorphic in Massalit." (PMID 20459687, 2010). "In this study isolates from both severe and uncomplicated malaria in Thailand could bind to CD36 while only 45% could bind to wild type ICAM-1 and at lower levels than to CD36." (PMID 19650937, 2009). "Plasmodium falciparum isolates from different geographical areas showed variable binding ability to CD36 and ICAM-1 and a wide range of ability to form rosettes, which may contribute to different clinical severity of malaria." (PMID 19650937, 2009). "Plasmodium falciparum isolates show different abilities to form rosettes and binding to CD36 and ICAM-1 which may contribute to different clinical severity of malaria." (PMID 19650937, 2009). "The aim of this study was to investigate the association of SNPs of three adhesion molecule genes, ICAM1, PECAM1 and CD36, with severity of falciparum malaria in a malaria-endemic and a non-endemic region of India." (PMID 19055786, 2008). "Besides CD36 that mediates non-opsonic phagocytosis, several other phagocyte receptors have been reported to be related to the phagocytic clearance of the malaria parasites." (PMID 41488299, 2025). "CD36 is the affinity of PfEMP1 protein, but is not present in Groups A and PfEMP1 B/A influencing extreme disease and also not in persons with reduced immunity to malaria." (PMID 35715862, 2022). "Moreover, at the activation phase, CD36 showed increased expression in the controls (34.44 [27.75–50.91]%) but decreased in the malaria groups (23.49 [18.98.70–44.75]%) without any significant difference." (PMID 32268918, 2020). "ICAM‐1 was blocked with antibodies in both HBMEC and HDMEC, while CD36 was blocked in HDMEC, and in all conditions, antibodies could block ~ 50% of adhesion independently of the parasites originating from cerebral malaria or uncomplicated malaria cases." (PMID 30804082, 2019). "Of note, histological analysis of malaria-infected Fyn −/− lungs revealed a lack of edema and septal thickening comparable to that observed in CD36−/− lungs despite having parasite numbers in the pulmonary vasculature that were comparable to that observed in the lungs from WT animals." (PMID 23967147, 2013). "In this study, to determine the role of CD36 in malaria immunity, we assessed the internalization of CD36-adherent and CD36-nonadherent Plasmodium falciparum-infected red blood cells (IRBCs) and production of pro-inflammatory cytokines by DCs, and the ability of DCs to activate NK, and T cells." (PMID 24204889, 2013). "Thus, the cellular and molecular basis for the CD36-dependent development of immunity to malaria remains not understood." (PMID 24204889, 2013). "Role of adhesion to CD36 in the physiopathology of severe malaria is still a subject of debate, as some studies have found higher binding in isolates infecting children with severe malaria and others in parasites infecting children with non-severe malaria." (PMID 21559373, 2011). "In addition, P. falciparum isolates from Thai adults suffering from severe but not cerebral malaria had higher CD36 adhesion than those from uncomplicated malaria patients." (PMID 18844973, 2008). "However, it is important to note that the correlation between severe malaria, the inability to bind to CD36 and group A var gene expression is not clear-cut." (PMID 18844973, 2008).